TAGLN2 (transgelin 2)
Diseases named in the same sentence as TAGLN2 in open-access papers (continued):
Sharing a sentence is not in itself a finding about the gene and the disease.
cancer (continued). "In fact, several reports using chemical compounds or microRNAs targeting the Tagln2 gene have shown potential positive results in the suppression of cancer development and metastasis." (PMID 33731208, 2021). "In agreement with this, transgelin-2 is considered a potential oncogenic factor in various cancer types." (PMID 33898417, 2021). "Taken together, these results suggest that transgelin-2 is not only important for tumorigenesis and cancer progression but is also essential for immune functions." (PMID 33731208, 2021). "It has also been observed that TAGLN2 is dysregulated in several malignancies and is involved in cancer cell proliferation, invasiveness, apoptosis, and metastasis." (PMID 34530821, 2021). "We demonstrated that the actin–transgelin-2–LFA-1 axis in cytotoxic CD8+ T cells is effective in potentiating adoptive T cell therapy in cases where cancer cells express ICAM-1 on their surface." (PMID 33731208, 2021). "These interesting features of transgelin-2 suggest that this small actin-binding protein acts as a double-edged sword in the context of cancer and immune cells." (PMID 33731208, 2021). "Because transgelin-2 expression contributes to cancer development, resistance, and metastasis, transgelin-2 is a potential target protein for anticancer therapy." (PMID 33898417, 2021). "The expression of transgelin-2 in cancer cells is different from that of immune cells, in which NF-κB pathway is dominant." (PMID 33898417, 2021). "Here, we review newly discovered molecular characteristics of transgelin-2 and discuss clinical applications for cancer and immunotherapy." (PMID 33898417, 2021). "One example is investigating how the transgelin-2-actin network regulates nuclear architecture for the expression and silencing of genes required for cancer cell growth." (PMID 33898417, 2021). "In contrast to the transgelin-1, in many studies, transgelin-2 expression was proposed as a potential cancer biomarker." (PMID 33898417, 2021). "This suggests that transgelin-2 can act as a double-edged sword depending on how we apply this protein to cancer therapy." (PMID 33731208, 2021). "Although the upregulation of transgelin-2 in cytotoxic T cells potentiates their cytotoxic activity, it does not increase the number of T-cell pools that selectively recognize cancer antigens." (PMID 33898417, 2021). "Transgelin-2 is an essential actin-binding protein for both immune function and cancer cell malignancy." (PMID 33898417, 2021). "In hypoxic cancer cells, Transgelin 2 (TAGLN2), an actin-binding protein, is induced, while in parallel, Snail1 is increased, leading to the induction of the EMT by downregulating the expression of E-cadherin." (PMID 33225905, 2020). "TAGLN2 mRNA levels were significantly lower in cancer vs normal and ARHGDIA and YWHAZ levels elevated significantly and non-significantly, respectively, in the same data set." (PMID 31043708, 2019). "Several studies have shown that high levels of transgelin-2 in cancer tissues are due to down-regulation of specific microRNAs." (PMID 30041673, 2018). "In recent years, dysregulated expression of transgelin-2 has been reported in different types of cancers." (PMID 30041673, 2018). "Consistent with our current study, TAGLN2 has been reported to be up-regulated and possess proto-oncogenic functions in a variety of cancers." (PMID 29110682, 2017). "KEGG analysis demonstrated that TAGLN2 was enriched in pathways in cancer, focal adhesion and regulation of the actin cytoskeleton." (PMID 29110682, 2017). "Perhaps because of its abundance, transgelin-2 has been frequently identified in proteomic profiling studies of cancer." (PMID 28521289, 2017). "It is worth further exploring the detailed molecular mechanisms of transgelin-2 in tumorigenesis and progression of cancer." (PMID 28521289, 2017). "In patient samples, TAGLN2 expression was enhanced in both cancer tissues and patient serums." (PMID 38509504, 2024).
cancer (continued). "To evaluate TAGLN2 expression in the stroma of surgical tissue, we performed an immunofluorescence (IF) study of surgical tissues with α-SMA, a representative marker of cancer-associated fibroblasts (CAFs), and TAGLN2." (PMID 38509504, 2024). "Overall, targeting TAGLN2 could be an appropriate therapeutic strategy against advanced cancer following chemotherapy failure." (PMID 38509504, 2024). "Furthermore, an analysis of the potential relationship between TAGLN2 expression and the infiltrating levels of different immune cells in various cancer types was conducted using the TIMER2.0 portal." (PMID 37476180, 2023). "Succeeding, the correlations of expression levels between TAGLN2 and immune-related genes that encode chemokines, chemokine receptors, immune-activating genes, immunosuppressive genes, and MHC genes were probed across different cancers." (PMID 37476180, 2023). "Thus, on the premise of the available public platforms, we operated a pan-cancer analysis, which provided valuable insights into the impact of TAGLN2 on multiple cancer types." (PMID 37476180, 2023). "Furthermore, it is now clear that the TAGLN2 status of the cancer cell has a profound involvement on the cancer immunity." (PMID 37476180, 2023). "Collectively, we postulated that TAGLN2 might be involved in remodeling the TME in certain types of cancer." (PMID 37476180, 2023). "Consequently, we are keen to further investigate more functions, mechanisms, and potential therapeutic objectives of TAGLN2 in diverse cancers by designing a range of in vitro and in vivo experiments, and finally incorporating them with clinical practice." (PMID 37476180, 2023). "Overall, our study is the first comprehensive analysis of TAGLN2 at pan-cancer." (PMID 37476180, 2023). "However, recent studies have reported that TAGLN2 can directly or indirectly participate in multiple cancer-related processes, including cell migration, proliferation, differentiation, and apoptosis." (PMID 37476180, 2023). "In the ascites of mice with metastatic ID8-Defb29/Vegfa OvCa, effector (CD62LlowCD44high) and central memory (CD62LhighCD44high) CD8+ T cells demonstrated a marked reduction in TAGLN2 expression, compared with the same T cell subsets in peritoneal lavage from cancer-free mice." (PMID 38168227, 2023). "Concerning the ESTIMATEScore, ImmuneScore, and StromalScore, we observed that TAGLN2 had a considerably positive association in a variety of cancers, but only a negative association in STAD and UCEC when employing the TCGA cohort." (PMID 37476180, 2023). "In addition, we also itemized the correlations between TAGLN2 and the major immune checkpoints in pan-cancer, including LAG3, PDCD1, CTLA4, CD274, and TIGIT." (PMID 37476180, 2023). "Furthermore, we found that the intracellular levels of TAGLN2 were significantly lower in CD8+ T cells isolated from the ascites of HGSOC patients than in peripheral CD8+ T cells from cancer-free women." (PMID 38168227, 2023). "Thus, the results suggested that TAGLN2 expression was elevated at both mRNA and protein levels in most of the cancers surveyed." (PMID 37476180, 2023). "The biological roles of transgelin-2 are not fully understood, but it is known that it is involved in apoptosis inhibition, induction of cell proliferation, and promotion of cancer metastasis, corresponding to stimulation of the expression of ABC transporters and PI3K/Akt kinase activity." (PMID 37762413, 2023). "Nevertheless, the exact mechanism of TAGLN2 in cancers remains largely unknown and research into it is still in its early stages." (PMID 37476180, 2023). "TAGLN2 is an oncogenic factor in various types of cancers and may be employed as a potential therapeutic target for CRC." (PMID 35720415, 2022). "However, a few reports demonstrated that transgelin-2 instead inhibits the motility of cancer cells, such as hepatocarcinoma cells, by suppressing actin polymerization." (PMID 33898417, 2021).
cancer (continued). "Therefore, transgelin-2 can act as a double-edged sword depending on how we apply this protein to cancer therapy." (PMID 33731208, 2021). "However, a few reports demonstrated that transgelin-2 inhibits the motility of cancer cells by suppressing actin polymerization." (PMID 35011306, 2021). "In cancer cells, however, these characteristics of transgelin-2 may be involved in the process of tumorization in a wide range of cancers." (PMID 33731208, 2021). "Reportedly, TAGLN2 plays an important role in malignant tumor invasion and metastasis." (PMID 34530821, 2021). "However, the precise mechanisms for the involvement of transgelin-2 in cancer development largely remain to be elucidated." (PMID 33898417, 2021). "Interestingly, however, transgelin-2 is also crucial for the induction of malignancy, metastasis, and invasion of cancer cells." (PMID 33898417, 2021). "Known and putative functions of transgelin-2 in immune and cancer cells." (PMID 33898417, 2021). "This work demonstrates that transgelin-2 is an essential protein for both cancer and immunity." (PMID 33731208, 2021). "The authors found that in endometrial and EOC BMs, the expression of alpha-enolase (ENO1) and triosephosphate isomerase (TPI-1) was higher and the expression of Transgelin-2 (TAGLN2) was lower compared to primary cancers, suggesting a role in development and progression of BMs." (PMID 34943916, 2021). "Their works are particularly interesting because the TSG12 can be applied to the activation of transgelin-2 function in immune cells, as it may also control the adhesion of T cells to the target cancer cells, thereby potentiating antitumor activity." (PMID 33898417, 2021). "These previous findings indicate that TAGLN2 may be a crucial regulator of metastasis and aggressiveness in malignancies." (PMID 34530821, 2021). "Gene transcription, miRNA regulation, or protein stability regulation may have different effects on transgelin-2 in different types of cancers." (PMID 30041673, 2018). "Through regulating cytoskeletal dynamics, transgelin-2 also participates in cancer metastasis." (PMID 28521289, 2017). "Several studies have demonstrated that transgelin-2 is dysregulated in various types of cancer." (PMID 28521289, 2017). "Moreover, fluorescence staining demonstrated that TAGLN2 knockdown decreased the formation of cell invadopodia, the F-actin-rich leading edge of invading cells, which is a key structure in cancer invasion." (PMID 29110682, 2017). "Previous studies show that transgelin 2 expression is decreased in some cancers." (PMID 24455688, 2013). "Both up- and downregulation of transgelin-2 may promote metastasis in various types of cancers." (PMID 37833976, 2023). "Furthermore, our study also uncovered the co-expression correlation of TAGLN2 with immune-related genes, including chemokine, chemokine receptor, MHC, immunostimulatory, and immunosuppressive genes, and the outcomes altogether showed that TAGLN2 is broadly involved in cancer immunity." (PMID 37476180, 2023). "Thus, our results based on functional network analysis and thus a predictive bioinformatic model could indicate that PRDX2, LCP1, OGN and TAGLN2 might impact the IPF progression through mechanisms common to cancer." (PMID 38322285, 2023). "Notably, TAGLN2 expression showed a positive correlation with macrophages, and cancer-associated fibroblasts, whereas a negative correlation with the infiltration degree of B cells." (PMID 37476180, 2023). "Similarly, the TAGLN2 DNA methylation landscape in pan-cancer was sketched." (PMID 37476180, 2023). "Importantly, transgelin-2 has previously been suggested as a molecular target protein that may have promising potential in cancer treatment." (PMID 35744062, 2022).
cancer (continued). "Compared with transgelin-1, however, because transgelin-2 is dominantly restricted to cancer cells, the strategy that selectively targets transgelin-2, instead of targeting the cytoskeleton itself, may diminish the potentially toxic side effects of cytoskeletal-directed cancer therapeutics." (PMID 33898417, 2021). "Because transgelin-2 is necessary for both immune cells and cancer cells to exert their optimal functions, the different expression mechanisms of transgelin-2 in immune cells and cancer cells suggest that these cells express transgelin-2 as a strategy for their survival, migration, and invasion." (PMID 33898417, 2021). "Interestingly, transgelin-2 is essential for both cancer development and immune functions." (PMID 33731208, 2021). "In this respect, transgelin-2 may be a promising target protein for cancer therapy." (PMID 33731208, 2021). "Furthermore, TAGLN2 also participates in the formation of an immunological synapse in T cells, maintains F-actin content, and blocks actin depolymerization, in a process similar to the formation of aggressive pseudopodia in malignant tumors." (PMID 34530821, 2021). "Although more aggressive studies are needed, if transgelin-2 in the nucleus controls cancer cell growth, exogenous treatment of cancer cells with cell-permeable transgelin-2, instead of reducing its expression by miRNAs, may help treat some cancers." (PMID 33898417, 2021). "Therefore, transgelin-2 can be an excellent molecular target in both immune cells and cancer cells." (PMID 33898417, 2021). "Thus, inhibition of transgelin-2 phosphorylation could be a potentially effective strategy for cancer treatment." (PMID 33898417, 2021). "Thus, an exciting future challenge is to understand whether this transgelin-2-mediated actin regulation in the nucleus controls cancer development and metastasis." (PMID 33898417, 2021). "Thus, targeting transgelin-2 can also have a therapeutic advantage for cancer treatment; selectively suppressing transgelin-2 expression may prevent multidrug resistance in cancer chemotherapy." (PMID 33898417, 2021). "Upregulation of transgelin-2 by cell-permeable recombinant protein in immune cells, downregulation by microRNA approaches in cancer cells may simultaneously improve immunity and defeat cancer cells." (PMID 33898417, 2021). "Therefore, although careful approach is certainly needed, the application of cell-permeable transgelin-2 peptide in DCs obtained from cancer patients may be an alternative method to boost DC function to enhance T cells and humoral immunity." (PMID 33898417, 2021). "The function of transgelin-2 in cancer cells is largely unknown." (PMID 30041673, 2018). "Furthermore, the identification of transgelin 2 in the regulation of angiogenesis may have important implications for vascular interventions, especially those for cancer treatment." (PMID 23056327, 2012). "Given the well-documented role of TGF-β in cancer pathogenesis, we explored its potential to regulate the coordinated activities of CXCR7 and TAGLN2 in PTC." (PMID 41169389, 2025). "Activation of GPER and reduction in the expressions of ROCK1, TAGLN2, and FCHO2 are some of the processes modulated by punicalagin that inhibit the development of cancer." (PMID 40018013, 2025). "Many operations, that is, activation of GPER and reduction of ROCK1, TAGLN2, and FCHO2 expressions, are involved in the prevention of cancer development." (PMID 40078339, 2025). "Nevertheless, further studies are required to understand the effect of TAGLN2 on the crosstalk between CAF and cancer cells." (PMID 38509504, 2024). "Moreover, persistent TAGLN2 expression might simulate a “pathological status of chronic infection”, and mediates immune-suppressive phenotype, which is likely to provide a new perspective for how cancer cells retain effects of prolonged IFN stimulation." (PMID 39168971, 2024).
cancer (continued). "Exposure to cell-free ascites supernatants from HGSOC patients drastically suppressed TAGLN2, IFNG, and GZMB expression in pre-activated CD8+ T cells obtained from peripheral blood of cancer-free women." (PMID 38168227, 2023). "After constructing a robust link between TAGLN2 and TME, we continued to use the GSEA analysis and GSVA analysis to explore the regulatory mechanism of TAGLN2 in the context of pan-cancer." (PMID 37476180, 2023). "The second subnetwork containing 13 nodes and 12 edges showed the interaction between PRDX2 and TAGLN2 as well as a mild increase in multiple components of the peroxisome (SOD1, CAT, PRDX5, PRDX1) and proteoglycans in cancer (FLNA, STAT3)." (PMID 38322285, 2023). "Here we report that the cytoskeletal organizer Transgelin 2 (TAGLN2) is necessary for optimal CD8+ T cell fatty acid uptake, mitochondrial respiration, and anti-cancer function." (PMID 38168227, 2023). "Accurately, a statistically significant positive correlation between TAGLN2 expression and TMB was observed in 6 cancer types, including ACC, THYM, SARC, SKCM, LGG, and BRCA, but TAGLN2 was negatively correlated to TMB in LUAD, and LAML." (PMID 37476180, 2023). "The functions of TAGLN2 and CRNN in different types of cancer have been studied in various literature." (PMID 37553345, 2023). "We identified that, at single-cell resolution, a positive correlation existed between TAGLN2 expression and functional states, such as EMT, metastasis, invasion, DNA damage, DNA repair, and hypoxia, across multiple cancers." (PMID 37476180, 2023). "To further validate the involvement of TAGLN2 in TME, we calculated the ESTIMATEScore, ImmuneScore, and StromalScore in 33 cancer types based on expression data profiles." (PMID 37476180, 2023). "As a result of these studies, novel biomarkers for cancer diagnosis [e.g. stathmin 1 (STMN1), transgelin 2 (TAGLN2)] or potential targets for therapeutic intervention were proposed (e.g. phosphoglycerate mutase 1 (PGAM1))." (PMID 29050215, 2017). "Upregulation of transgelin-2 predicts poor survival of patients with PDAC, and demonstrates that transgelin-2 is involved in cancer progression." (PMID 28521289, 2017). "Previous studies have suggested that overexpression of TAGLN2 is a potential cause of chemoresistance by increasing EMT properties; however, the mechanism of cancer development and chemoresistance by TAGLN2 has not yet been identified." (PMID 38509504, 2024). "TAGLN2, a member of the actin-binding protein family, although not fully understood, plays a role in cancer by being upregulated in response to external inflammatory signals." (PMID 39168971, 2024). "Besides, we identified TAGLN2 correlated to TME, immune cell infiltration, immune-relevant genes, TMB, and MSI, suggesting an immunoregulatory role in cancers." (PMID 37476180, 2023). "And the mechanism of TAGLN2 in cancer was mainly from bioinformatics analysis without laboratory confirmation." (PMID 37476180, 2023). "Thus, we evaluated the connection between TAGLN2 and TMB, as well as MSI across 33 cancer types and depicted the data in the form of Rader graphs and scatter plotters." (PMID 37476180, 2023). "MiR-145 could directly bind to TAGLN2 to suppress BC cell proliferation and migration and silence c-Myc to inhibit the PTBP1/PKMs Axis, thereby reducing the cancer-specific energy metabolism." (PMID 30871066, 2019). "Finally, GSEA analysis revealed that high levels of TAGLN2 were significantly related to EMT, cancer metastasis, and the G1-S phase transition of cell cycle progression." (PMID 29110682, 2017). "We focused on TAGLN2 and not the top ranked gene (SERP1), because the latter was not reported to be associated with carcinoma." (PMID 21378409, 2011). "Further, we investigated whether the non-viral transduction of cell-permeable transgelin-2 peptide potentially enhance DC-based cancer immunotherapy." (PMID 33731208, 2021).